EZH2 (enhancer of zeste 2 polycomb repressive complex 2 subunit)
Diseases named in the same sentence as EZH2 in open-access papers (continued):
Sharing a sentence is not in itself a finding about the gene and the disease.
synovial sarcoma (continued). "As the deficiency in SMARCB1 expression was the original hypothesis that led us to investigate the use of EZH2 inhibitors in synovial sarcoma, this may explain the differential sensitivity observed in this model." (PMID 27391784, 2016). "We next explored RNA knockdown and pharmacologic inhibition EZH2 in synovial sarcoma in vitro." (PMID 27125524, 2016). "Treatment of mice bearing either a cell line or two patient-derived xenograft models of synovial sarcoma leads to dose-dependent tumor growth inhibition with correlative inhibition of trimethylation levels of the EZH2-specific substrate, lysine 27 on histone H3." (PMID 27391784, 2016). "In this report, we investigate the potential that synovial sarcomas, due to their deficiency in SMARCB1, may be dependent on EZH2 activity." (PMID 27391784, 2016). "Thus, synovial sarcoma in vivo models display overlapping EZH2 inhibitor-induced changes in gene expression, suggesting a common mechanism for the antitumor activity of EZH2 inhibition." (PMID 27391784, 2016). "In this study, we first confirmed EZH2 expression in the 76% of human synovial sarcoma samples." (PMID 27125524, 2016). "We sought to confirm that high-level EZH2 expression is present in human synovial sarcoma samples." (PMID 27125524, 2016). "Later, overexpressed EZH2 may become a therapeutic target in synovial sarcoma, especially when inhibited in combination with other pro-oncogenic epigenetic modulators." (PMID 23110793, 2012). "Intriguing hypotheses have recently been formulated on the collaboration between EZH2 and SYT-SSX, the chimeric gene diagnostic of synovial sarcoma." (PMID 23110793, 2012). "EZH2 overexpression in synovial sarcoma is correlated with high H3K27 trimethylation." (PMID 23110793, 2012). "Lastly, EZH2 as a highly expressed pro-oncogenic regulator may also be an attractive candidate target for the future therapy of synovial sarcoma." (PMID 23110793, 2012). "EGR1 repression has been found to be associated with H3K27 trimethylation, and EZH2 and the PRC1 component BMI1 have been shown to directly bind its promoter, thus supporting the existence of a novel epigenetic mechanism of oncogenesis in synovial sarcoma." (PMID 21609503, 2011). "However, if epigenetic mechanisms play a major role in the oncogenesis of synovial sarcomas, the synergy of epigenetic drugs with ICI should be assessed in this tumor type, for example with an association of EZH2 inhibitors and ICI in tumors overexpressing EZH2." (PMID 34925348, 2021). "Additionally, the absence of mutations in EZH2 in these two synovial sarcoma cell lines was confirmed by sequencing." (PMID 27391784, 2016). "Furthermore, two PDX models of synovial sarcoma displayed sensitivity to EZH2 inhibition." (PMID 27391784, 2016). "However, although the synovial sarcoma fusion proteins SYT-SSX1/2/4 are known to interact with PcG members, the diagnostic and prognostic significance of EZH2 expression in synovial sarcoma has not yet been investigated." (PMID 23110793, 2012). "Clinical trials of EZH2 inhibitors have begun, along with investigations of these inhibitors for STS, including synovial sarcoma." (PMID 30487384, 2018). "EZH2 siRNA was transfected into Yamato-SS, Aska-SS, and SYO-1 synovial sarcoma cell lines as described." (PMID 27125524, 2016). "EGR1 is repressed by the SS18-SSX fusion protein in synovial sarcoma in that SS18-SSX recruits PcG proteins, including EZH2 and Bmi1, to the EGR1 promoter and correlates with H3K27me338." (PMID 27125524, 2016). "This suggests that SS18-SSX translocation containing synovial sarcoma cell lines are dependent on the activity of the PRC2 complex and EZH2 for their survival." (PMID 27391784, 2016). "We observed that EZH2 inhibition did not lead to a significant change in SOX2 expression in any of the synovial sarcoma cell lines examined." (PMID 27391784, 2016).
synovial sarcoma (continued). "We have previously shown that SMARCB1-negative MRT tumors are dependent on EZH2 activity, and we therefore investigated whether the synovial sarcoma cell lines, with decreased SMARCB1 expression, would likewise display a similar sensitivity to EZH2 inhibition." (PMID 27391784, 2016). "Consistent with this view, blocking EZH2 activity with small molecules (such as EPZ005687 and tazemetostat) was reported to induce the removal of repressive histone marks and subsequent activation of some tumor suppressor genes usually repressed by SS18-SSX in synovial sarcoma cells." (PMID 40296913, 2025). "Thus, EZH2 inhibition does not change SOX2 expression in SS18-SSX positive synovial sarcoma cell lines, but is able to reverse some synovial sarcoma-specific gene expression, at least ATF3, and others less consistently across models." (PMID 27391784, 2016).
viral infection (25 papers, 2015 to 2026). "Ezh2 inhibition resulted in increased frequency of IFN-γ producing tumor-infiltrating CD8+ T cells, whereas Ezh2-deficient CD8+ T cells exhibit an impaired ability to produce IFN-γ in a virus infection model." (PMID 34305954, 2021). "Differential expression of EZH2 as a result of upregulation of let-7e expression was implicated in several viral infections including DENV2 infected peripheral blood mononuclear cells (PBMCs)." (PMID 31954402, 2020). "Further, rs17198965 resides in the binding motif for the transcription factor EZH2, which suppresses major MHC class I molecule expression and is crucial for initiating CD4+ T cell-associated response upon viral infection." (PMID 37415598, 2023). "We set out to elucidate the epigenetic role of EZH2 in TFH cells and identify the downstream regulators modulated by EZH2 during acute viral infection." (PMID 36045674, 2022). "In summary, this study reveals for the first time that EZH2 regulates the epigenetic modification of Tcf7 during acute viral infection." (PMID 36045674, 2022). "Next, we conducted loss-of-function assays for EZH1 and EZH2 using lentivirus-mediated shRNA in Huh7 and HepG2 cells, successfully achieving stable knockdown of EZH1 and EZH2 using RFP and EGFP as a viral infection marker, respectively." (PMID 34725436, 2021). "Together, these results indicated that impaired mTOR activity contributes to the poor expansion of virus-specific CD4 T cells devoid of EZH2 protein upon viral infection." (PMID 32999031, 2020). "Next, we sought to explore the role of EZH2 in the late differentiated phase/memory phase of the CD4 T cell response to acute viral infection." (PMID 32999031, 2020). "Here, we found that EZH2 is integral for virus-specific CD4 T cell expansion in a mouse model of acute viral infection." (PMID 32999031, 2020). "Collectively, these data demonstrated that an abundance of EZH2 protein accelerates early-activated CD4 T cell expansion in acute viral infection." (PMID 32999031, 2020). "Particularly, during the CD4 T cell response to acute viral infection, EZH2 spikes within 3 days after infection and declines to a basal level comparable to that in the naive state at day 8 postinfection." (PMID 32999031, 2020). "In conclusion, our present study demonstrates that the epigenetic regulator EZH2 is integral for CD4 T cell expansion during acute viral infection." (PMID 32999031, 2020). "Altogether, these data highlighted the importance of cell-intrinsic EZH2 in the mechanism regulating endogenous TFH differentiation in response to an acute viral infection." (PMID 30842630, 2020). "Here, we also found that EZH2 is indispensable for mTOR signal activation in CD4 T cells during acute viral infection." (PMID 32999031, 2020). "With EZH2 deficiency-induced inadequate energy support, the CD4 T cell response to acute viral infection is largely diminished." (PMID 32999031, 2020). "Following in vivo stimulation by viral infection, Ezh2 was potently induced after CD4+ T cell activation, even before cell division, similar to the induction of CD25." (PMID 30575739, 2018). "Meanwhile, stable expression of EZH2 by virus infection (EZH2 +/+) decreased the induction of both p21 mRNA and protein levels after the drug treatment, as evidenced by the luciferase activity and IB analysis, respectively." (PMID 27882937, 2016). "While previous studies have established EZH2's role in viral infection and innate immune responses, its function in PCV2 infection remains unclear." (PMID 42260657, 2026). "Interestingly, recent studies suggest that inhibition of EZH2/1 can induce an antiviral state in human foreskin fibroblast cells and affect viral infection." (PMID 36768720, 2023). "Therefore, our findings suggested that EZH2 plays an important role in maintenance of hypomethylation at Tcf7 locus thus affecting TFH differentiation during acute viral infection." (PMID 36045674, 2022).
viral infection (continued). "Since TFH cells are critical in humoral immunity responses and development of autoimmune diseases, the dissection of EZH2 function may provide substantial therapeutic benefits for the treatment of viral infection and autoimmune diseases." (PMID 36045674, 2022). "EZH2 promotes the polarization of mouse Tfh cells during viral infection." (PMID 35795677, 2022). "Interestingly, our bioinformatics analysis found that after inhibiting EZH2, many viral infection-related processes were also activated, including COVID19, Epstein-Barr virus and viral protein interaction with cytokine and cytokine receptor." (PMID 33794893, 2021). "EZH2 is crucial for CD4 T cell response during acute viral infection." (PMID 32999031, 2020). "EZH2 is indispensable for the metabolic fitness of CD4 T cells in acute viral infection." (PMID 32999031, 2020). "Therefore, we identified the chromatin-modifying enzyme EZH2 as a novel regulator of early TFH differentiation during acute viral infection." (PMID 30842630, 2020). "To test this hypothesis, we bred Ezh2fl/fl or Ezh2fl/flCd4-Cre mice with SM mice to probe the role of EZH2 in CD4 T cell responses to acute viral infection." (PMID 32999031, 2020). "Importantly, early fate-committed TFH cells exhibited higher expression of the histone methyltransferase EZH2 in response to an acute viral infection and accordingly increased levels of the H3K27me3 modification compared with that of their TH1 counterparts." (PMID 30842630, 2020). "Thus, we identified EZH2 as a novel regulator in virus-specific CD4 T cell expansion during acute viral infection." (PMID 32999031, 2020). "Next, we investigated whether the inhibition of the EZH2-mediated H3K27me3 modification also led to defects in the TFH cell commitment of virus-specific CD4+ T cells in response to a viral infection." (PMID 30842630, 2020). "Thus, our results pinpointed EZH2 as a crucial hub in fostering the CD4 T cell response in the early expansion phase during acute viral infection." (PMID 32999031, 2020). "It is of note that Ezh2-mediated p19Arf repression appears to function specifically in TFH cells since dual targeting of p19Arf and Ezh2 did not boost accumulation of Ezh2-deficient TH1 or effector CD8+ T cells in response to viral infection." (PMID 30575739, 2018). "A recent study linked a non-enzymatic effect of EZH2 to regulation of the innate response to virus infection." (PMID 26030458, 2015). "In this study, we determined the global transcriptomic and epigenomic alterations in AMs after EZH2 inhibition using porcine 3D4/21 AM cells as a model, focusing on the coinciding immune activation and retrotransposon derepression, and the influence on viral infection." (PMID 36768720, 2023). "Viral infections alter the expression of lysine demethylase 2B (KDM2B/NDY1), enhancer of zeste 2 polycomb repressive complex 2 subunit (EZH2) and JARID2." (PMID 39420919, 2024). "The genetic ablation of EZH2 leads to impaired cellular metabolism and, consequently, poor CD4 T cell response to acute viral infection." (PMID 32999031, 2020). "It has also been recently reported that inhibitors of the histone methyltransferase activity of EZH2 can suppress infection by several viruses, suggesting a function of EZH2 and/or PRC2 in regulating viral infection." (PMID 32873321, 2020). "We did not detect localization of EHMT2 or Ezh2, another epigenetic modifier into viral IBs in response to viral infection indicating that this was not a common observation among all the epigenetic modifiers." (PMID 39509467, 2024). "To determine whether the DNA methylation pathway in TFH cells is affected by EZH2 deletion, we measured the expression of DNA methyltransferases in TFH cells derived from control and Ezh2-/- mice on day 8 after acute viral infection." (PMID 36045674, 2022).
viral infection (continued). "Taken together, the data indicated that EZH2 acts as an indispensable regulator to preserve metabolic fitness by coordinating mitochondrial respiration, glycolysis, and fatty acid synthesis in CD4 T cells during acute viral infection." (PMID 32999031, 2020). "Considering the positive correlation between the EZH2 expression level and TFH commitment, we next investigated whether EZH2 is indeed essential for early TFH differentiation upon acute viral infection." (PMID 30842630, 2020). "In addition to the crucial role of EZH2 in TFH/TH1 cell differentiation, the present study also found that EZH2 is a prerequisite for the efficient expansion of CD4 T cells (including both TFH and TH1 cells) during acute viral infection." (PMID 32999031, 2020). "The purpose of this review is to instead focus on the role of EZH2 in CD8+ T cell differentiation and effector function in the context of viral infection and cancer, comparing and contrasting phenotypes observed across multiple models to give greater insight into EZH2 biology." (PMID 33117406, 2020). "Given that interferon response is important for the inhibition of viral infection, we further revealed that IAV infection is remarkably suppressed in the porcine AMs pre-treated with EZH2, which suggests the enhanced antiviral state in the porcine AMs after inhibition of EZH2." (PMID 36768720, 2023). "In addition, histone methyltransferase EZH2 has also been reported to regulate CD8+ T cell differentiation and function in viral infections or cancer, but the impact of perturbing T cell-intrinsic EZH2 on T cell response to PD-1 blockade remains unclear." (PMID 34819502, 2021). "We found enhanced EZH2 expression in recalled SM CD4 TFH cells and TH1 cells compared to basal EZH2 expression levels in unrecalled ones, suggesting EZH2 might play an important role in regulating CD4 T cell recall responses in acute viral infection." (PMID 32999031, 2020). "The EZH2 protein reached peak levels at day 2.5 and then declined to a basal level at day 8, suggesting EZH2 might play a role in regulating virus-specific CD4 T cell responses during the early phase of an acute viral infection." (PMID 32999031, 2020). "Taken together, these data validated the hypothesis that EZH2 expression and the subsequent H3K27me3 modification in virus-specific CD4+ T cells were important for early commitment to the TFH cell fate in response to an acute viral infection." (PMID 30842630, 2020). "In addition, specific ablation of either Tcf1 or Ezh2 in mature CD4+ T cells impaired TFH differentiation, and targeting both proteins almost completely abrogated the TFH cell formation and Bcl6 induction elicited by viral infection." (PMID 30575739, 2018). "Hence, EZH2 is not required for the late differentiation and the maintenance of virus-specific TFH cells in response to an acute viral infection, suggesting a specific effect on early TFH fate commitment." (PMID 30842630, 2020).
lupus (24 papers, 2011 to 2025). "In an allogeneic T-cell-induced lupus model, deficiency or pharmacological inhibition of EZH2 suppresses GC formation and autoantibody production." (PMID 36220996, 2022). "EZH2 is abnormally elevated in lupus and is associated with immune homeostasis imbalance and disruption of autoimmune tolerance in SLE patients." (PMID 36313363, 2022). "EZH2 deficiency in a lupus-like chronic graft versus host disease mouse model significantly reduces Tfh cells and suppresses antibody production and germinal center formation." (PMID 35795677, 2022). "Inhibition of EZH2 by 3-DZNep significantly reduced the number of pathogenic double negative T cells and production of cytokines and chemokines in lupus prone MRL/lpr mice." (PMID 33679454, 2021). "EZH2 is associated with decreased CD8 cytotoxic function in lupus-infected patients." (PMID 36313363, 2022). "The pathogenic role of EZH2 in lupus may be in part due to its promotion of PC differentiation and antibody secretion." (PMID 33519824, 2020). "Finally, EZH2-mediated epigenetic dysregulation in naïve CD4+ T cells from SLE patients that are associated with increased disease activity suggest a role for EZH2 overexpression in lupus flares." (PMID 32395334, 2020). "Previous reports have demonstrated that EZH2 can regulate DNA methylation in lupus patients and control T cell adhesion by connecting with adhesion molecule A." (PMID 38886655, 2024). "BCL-6 attaches to the promoter region of miR-142 in CD4+ T cells in lupus and recruits EZH2 and HDAC5, which leads to the upregulation of H3K27me3 and the downregulation of H3K9/K14ac, respectively." (PMID 35637283, 2022). "And EZH2-inhibitor suppresses autoantibody production and GC formation in bm12 induced lupus-like chronic graft-versus-host disease (cGVHD)." (PMID 36313363, 2022). "A new mechanism revealed by us indicates that BCL-6 recruits EZH2 to the promoter of miR-142 in CD4 + T cells in lupus to increase the expression of miR-142-3p/5p." (PMID 35637283, 2022). "Although the inhibition of EZH2damages the function of Tregs, animal experiments confirm that the application of EZH2 inhibitors in lupus mice can inhibit autoimmunity and improve lupus-related symptoms." (PMID 36313363, 2022). "Overall, we provided supporting evidence that BCL-6 is a novel factor participating in the pathogenesis of lupus by epigenetically suppressing miR-142-3p/5p expression with the help of EZH2 in CD4+ T cells." (PMID 35637283, 2022). "MRL/lpr mice treated with EZH2 inhibitors exhibit lowered anti-dsDNA antibodies, decreased inflammatory cytokines, improved symptoms, and reduced mortality, indicating that EZH2 is a promising therapeutic target for lupus." (PMID 36313363, 2022). "EZH2 expression is elevated in CD4+ T cells in lupus, leading to increased cytokine secretion and increased T cell adhesion." (PMID 36313363, 2022). "Nevertheless, the study of regulatory networks involving BCL-6 and EZH2 in lupus remains a major challenge at the genome level." (PMID 35637283, 2022). "We evaluated the therapeutic effects of EZH2 inhibitor in NZB/NZW F1 mice which depend on IFN-I signaling pathway for the lupus-like disease development." (PMID 33868295, 2021). "In Systemic Lupus Erythematosus (SLE), the association of miRNAs dysregulation with T cells phenotype alterations has been explained by variations in the expression of their target genes involved in epigenetic mechanisms, such as DNMTs and EZH2." (PMID 33602320, 2021). "Data presented here indicate that Ezh2 gene deletion or pharmacological Ezh2 inhibition suppresses autoantibody production and GC formation in bm12 induced lupus-like cGVH disease." (PMID 32503684, 2020). "Ezh2 is upregulated in multiple cell types in lupus patients and is known to be important in T cell differentiation and function and in GC B cell proliferation." (PMID 32503684, 2020).